SIRT1 (sirtuin 1)
Diseases named in the same sentence as SIRT1 in open-access papers (continued):
Sharing a sentence is not in itself a finding about the gene and the disease.
metabolic syndrome (continued). "Moreover, we showed that regulation of the Sirt1-PPARα-IGFBP-2 signaling cascade by AMPK activator represents a novel pathway that could be applied to ameliorate metabolic syndromes by controlling IGF-1 homeostasis." (PMID 27009398, 2016). "Importantly, transgenic Sirt1 mice had shown resistance in developing metabolic syndrome." (PMID 23840225, 2013). "This study is the first to investigate the potential protective role of combined treatment with E1231 acting as a direct SIRT1 activator and NMN acting as an SIRT1 stabilizer on metabolic syndrome." (PMID 40166461, 2025). "Therefore, although it is true that the functional effect that both SNVs have on the associated protein is still being investigated, the data obtained in our study indicate that the SIRT1 genetic variants could have a possible non-risk effect for dyslipidemia." (PMID 38645486, 2024). "These insights support the rational design of new candidates targeting the Glu230 residue in SIRT1 NTD to inhibit endothelial inflammation and related complications in metabolic syndrome." (PMID 39635433, 2024). "Moreover, SIRT1 could confront metabolic syndrome by inhibiting inflammation." (PMID 36581622, 2022). "In contrast, hepatocyte SIRT1 was dispensable for NAMPT to produce therapeutic effects on light-cycle thermogenesis, dyslipidemia, and hepatic de novo lipogenesis." (PMID 35228549, 2022). "AL-LSGJ improved adiposity by increasing adipocyte SIRT1 mRNA expression involved in FAO, which contributed to reduce the dyslipidemia and inflammation." (PMID 30463250, 2018). "It was reported that the expression of SIRT1 and SIRT2 in metabolic syndrome rats was reduced in white adipose tissue at six months old." (PMID 30424542, 2018). "Furthermore, PDPs provided detailed insights into how the individual parameters IRS-1, SIRT1, and p-AKT exhibit strong inverse relationships with metabolic syndrome." (PMID 40166461, 2025). "In this study, liver SIRT1 and PCG-1α are downregulated in cinnamon-treated rats, which may indirectly lead to their dyslipidemia." (PMID 34306160, 2021). "In this study, we identified the SIRT1-dependent or independent PGC-1α pathways in multiple organs that mediate the protective effects of a strain of Lactobacillus plantarum against high-fat diet-induced adiposity, glucose intolerance, and dyslipidemia." (PMID 32040532, 2020). "The therapeutic prospects for using activators of Sirt1 in the treatment of disease outcomes of metabolic syndrome have not been conclusive to date." (PMID 32796716, 2020). "Regardless, these conflicting studies do not undermine the importance of SIRT1 in the liver and the use of SIRT1 agonists or fasting-like mimetics as possible therapeutic options for patients with metabolic syndrome." (PMID 33193730, 2020). "In mammals, although whole body overexpression of SIRT1 in mice protects from the metabolic syndrome, it does not affect lifespan, whereas overexpression in brain induces longevity." (PMID 30463299, 2018). "In peripheral blood mononuclear cells (PBMCs), the expression levels of the SIRT1 were lower in subjects with metabolic syndrome than in subjects without metabolic syndrome." (PMID 25360511, 2014). "Activators of SIRT1 might have therapeutic potential in treating metabolic syndrome-related outcomes, although results have not been acknowledged to date." (PMID 40166461, 2025). "Furthermore, SIRT1 knockdown completely regained the RSV-elevated PRDM16 protein, as well as the RSV-increased CIDEA and TMEM26 mRNA, suggesting the indispensable and primary role of SIRT1 in RSV-mediated regulation of metabolic syndrome." (PMID 33805912, 2021). "However, SIRT1 overexpression does not have a significant effect on adipokine secretion in a metabolic syndrome rat model." (PMID 33204398, 2020).
metabolic syndrome (continued). "The network analysis further highlights these relationships, with strong negative correlations (blue lines) between SIRT1, Nrf2, and p-AKT with markers like NFκB, HOMA-IR, and SBP, reinforcing the protective role of these signaling pathways in the context of metabolic syndrome." (PMID 40166461, 2025).
cardiac hypertrophy (135 papers, 2009 to 2026). "Apart from this function, IL-6 causes cardiac muscle dysfunction through the sirtuin 1 pathway and promotes cardiac hypertrophy through the activation of fgp130." (PMID 39456869, 2024). "More importantly, SIRT1-FoxO1-mediated autophagy is the primary mechanism underlying GB's cardioprotective effect in cardiac hypertrophy." (PMID 34257705, 2021). "It has also been reported that in humans, SIRT1 levels increase in (chronic) hypertension, which is associated with cardiac hypertrophy." (PMID 34730891, 2021). "The overexpression of Sirt1 has been shown to favor the survival of cardiomyocytes, but to be also associated with cardiac hypertrophy and HF." (PMID 33238655, 2020). "The efficacy of vitamin D3 against diabetes-associated cardiac hypertrophy is mediated by increased sirtuin-1, in association with attenuated DNA oxidative damage, decreased PARP1 and lower mammalian target of rapamycin (mTOR) phosphorylation." (PMID 31434333, 2019). "Consistently with these observations, in Sirt1-deficient mice it has been shown that after physical exercise cardiac hypertrophy was prevented or reduced." (PMID 30304806, 2018). "Research has proposed that circ-SIRT1 can promote autophagy in human-induced pluripotent stem cell-derived cardiomyocytes (hiPSC-CMs) and H9c2 cardiomyocytes by activating SIRT1, thus mitigating Ang II-induced cardiac hypertrophy (CH), based on the finding that autophagy deficiency leads to CH." (PMID 40316538, 2025). "ISM1 lost its protective effects against cardiac hypertrophy and fibrosis after SIRT1 deficiency." (PMID 38300636, 2024). "Finally, researchers have proposed that SIRT1 influences cardiac function through its association with regulating energy metabolism and cardiac hypertrophy and its demonstrated protective effect against oxidative stress." (PMID 38791311, 2024). "In our study, in obese patients with pre-diabetic condition the cardiac hypertrophy and the cardiac dysfunction may be linked to reduced adipose tissue levels of SIRT1." (PMID 30246793, 2018). "SIRT1 upregulation is associated with cardioprotection since heart-specific SIRT1 overexpression protects the heart against cardiac dysfunction and cell death, cardiac hypertrophy, and mediates the cardioprotective effects of ischemic preconditioning." (PMID 30131726, 2018). "Sirt1 deficiency results in activation of proliferative and proinflammatory pathways involving tumour necrosis factor-α and nuclear factor-κB (NF-κB), leading to cardiac hypertrophy, fibrosis, and heart failure." (PMID 29234485, 2017). "Increase of Sirt1 expression in the heart was associated with cardiac hypertrophy, however, the constitutive high level of Sirt1 may be harmful to the heart itself and reduce cardiac function, proved by transgenic model." (PMID 24913149, 2014). "It has been shown that moderate overexpression of SIRT1 decreased age-dependent apoptosis/fibrosis, senescence markers, cardiac hypertrophy, and cardiac dysfunction." (PMID 41567643, 2025). "As well, knockout of SIRT1 in mice led eventually to impaired cardiac function, cardiac hypertrophy and arrhythmia, implying the correlation between increased SERCA2a crotonylation mediated by SIRT1 and these pathological outcomes." (PMID 38440918, 2025). "Western blot analysis revealed that Ang II treatment markedly suppressed the expression of pAMPK and SIRT1 proteins in cardiomyocytes, which was accompanied by an upregulation of the cardiac hypertrophy marker BNP." (PMID 41010549, 2025). "During cardiac hypertrophy, the expression levels of SIRT1, SIRT3, and PGC-1α (peroxisome proliferator-activated receptor γ-coactivator 1α) are significantly reduced." (PMID 40710369, 2025).
cardiac hypertrophy (continued). "In murine models, low to moderate cardiac-specific overexpression of Sirt1 has been shown to effectively alleviate age-related progression of cardiac hypertrophy, fibrosis, apoptosis, and decline in cardiac function." (PMID 40087582, 2025). "To better determine the role of SIRT1 in pathological cardiac hypertrophy, we knocked out SIRT1 expression in mice." (PMID 38278820, 2024). "Overexpression of SIRT1 inhibited Ang II-induced pathological cardiac hypertrophy by reducing cardiomyocyte apoptosis and promoting autophagy." (PMID 38278820, 2024). "The SIRT1:PPARα interaction was protective in cardiac hypertrophy and the deregulation of its related signaling pathway was associated with reduced fatty acid oxidation in the liver." (PMID 38534754, 2024). "The expression of the Sirtuin 1 gene (SIRT1) was found to regulate various cardiovascular diseases (CVDs) such as cardiac hypertrophy (CH), ischemia–reperfusion injury, and vasculitis." (PMID 39452835, 2024). "Studies have found that SIRT1 exhibits different or even opposite functions in pathological cardiac hypertrophy." (PMID 38278820, 2024). "Ang-II has been shown to induce mitochondrial dysfunction and alter cardiac substrate use and the metabolomic profile in cardiac hypertrophy involving Sirtuin 1 (SIRT1)." (PMID 38397106, 2024). "SIRT1 can prevent cardiac hypertrophy and myocardial fibrosis after being activated, while SIRT activators have not been found so far." (PMID 39062982, 2024). "Studies have shown that overexpression of SIRT1 in the heart can attenuate age-dependent increases in cardiac hypertrophy." (PMID 38813367, 2024). "While the enhancement of SIRT1 expression has advantages in MIRI treatment, extreme overexpression of SIRT1 has been reported to lead to disadvantages such as hypertrophy and cardiac dysfunction." (PMID 39769255, 2024). "Here, we identified a novel mechanism of CTRP3 against cardiac hypertrophy by activating UPRmt via the SIRT1/ATF5 axis." (PMID 38278820, 2024). "For instance, MC1R regulates brain injury by modulating mitochondrial metabolism through this pathway, while acacetin alleviates cardiac hypertrophy via AMPK/SIRT1/PGC‐1α." (PMID 39325807, 2024). "Our study demonstrates that CTRP3 activates UPRmt via the SIRT1/ATF5 axis under pathological myocardial hypertrophy, thus attenuating mitochondrial dysfunction and oxidative stress injury." (PMID 38278820, 2024). "Endogenous FGF21 protects against cardiac hypertrophy via the sirtuin 1 (SIRT1)–peroxisome proliferator-activated receptor α (PPAR-α) pathway." (PMID 36926038, 2023). "Overexpression of SIRT1 is a very effective way to counteract angiotensin-II-induced myocardial hypertrophy." (PMID 37762053, 2023). "Ang-II induces cardiac hypertrophy by suppressing SIRT1 expression, whereas ginkgolide B counteracts it by enhancing autophagy through the activation of the SIRT1-FoxO1 pathway." (PMID 36843938, 2023). "SIRT1 can alleviate myocardial hypertrophy by mediating redox regulators as well as inflammatory body inhibitors." (PMID 37691190, 2023). "PARP-1 contributes to caspase-independent myocyte cell death during heart failure while knockdown of PARP-2 protects against cardiac hypertrophy via SIRT1 activation." (PMID 37219631, 2023). "Conversely, metabolism was inversely correlated with cardiac structural and diastole, except by SIRT1 which showed a positive correlation with hypertrophy and diastolic dysfunction indicators." (PMID 37654004, 2023). "Obese mice show significant cardiac hypertrophy, inflammatory cell infiltration, reduced SIRT1 activity, altered mitochondrial signaling and oxidative homeostasis, and overexpression of inflammatory markers." (PMID 36843938, 2023). "A study using angiopoietin 2-induced cardiac hypertrophy mice noted that FGF21 treatment increased SIRT1 deacetylation activity, promoted AMPK phosphorylation, and reduced cardiac hypertrophy in a SIRT1-dependent pathway." (PMID 37416922, 2023).
cardiac hypertrophy (continued). "According to experimental data, overexpression of SIRT1 from low (2.5-fold) to moderate (7.5-fold) prevents myocardial hypertrophy, development of apoptosis/fibrosis, and heart failure and decreases expression of aging markers." (PMID 38139440, 2023). "In conclusion, our study provides the first evidence that FGF20 not only act as sensor for pressure-induced cardiac hypertrophy, but also maintains redox homeostasis by activating SIRT1-mediated antioxidant defenses." (PMID 35351862, 2022). "Previous studies suggest that SIRT1 is an important myocardial protective factor and that SIRT1 activation prevents the progression of pathological cardiac hypertrophy." (PMID 35351862, 2022). "To validate that the regulatory effects of FGF20 on pathological cardiac hypertrophy were SIRT1-dependent, we generated SIRT1 flox/flox (SIRT1fl/fl) mice and inducible cardiac-specific SIRT1 knockout (SIRT1-iKO) mice." (PMID 35351862, 2022). "Study had found that the over expression of Sirt1 can reduce myocardial hypertrophy and interstitial fibrosis." (PMID 35081907, 2022). "As a stress sensor, the NAD+-dependent deacetylase Sirtuin 1 (SIRT1) has been shown to be cardioprotective in response to a number of cardiac insults including ischemia, pressure overload, cardiac hypertrophy, or aging." (PMID 35743074, 2022). "Available evidence suggests that SIRT1 plays a protective role in cardiac hypertrophy induced by pressure overload." (PMID 36204518, 2022). "Activation and agonists of SIRT1 attenuate oxidative stress and protect against cardiac hypertrophy and heart failure." (PMID 35351862, 2022). "It has previously been observed that HK reduces oxidative stress and reverses cardiac hypertrophy by activating Sirt1 and Sirt3, respectively." (PMID 35264952, 2022). "Interfering with the LKB1/AMPK/Sirt1 axis abated the lncRNA NBR2-mediated inhibitory effect on myocardial hypertrophy and ER stress." (PMID 35703318, 2022). "Honokiol (HK) has previously been reported to improve myocardial ischemia/reperfusion injury and reverse myocardial hypertrophy by activating Sirt1 and Sirt3." (PMID 35264952, 2022). "Taken together, these data demonstrate that FGF20-mediated prevention of cardiac hypertrophy is related to SIRT1 activation." (PMID 35351862, 2022). "It has previously been observed that HK reduces oxidative stress and reverses cardiac hypertrophy by activating Sirt1, Sirt3, and Nrf2, respectively." (PMID 35264952, 2022). "Overexpressing NBR2 significantly restrained Ang II–induced myocardial hypertrophy by motivating the LKB1/AMPK/Sirt1 pathway." (PMID 35703318, 2022). "Some studies have testified that activation or attenuation of MAPK modulates cardiac energy metabolism through the Sirt1 pathway, thus mitigating or aggravating myocardial hypertrophy." (PMID 35703318, 2022). "SIRT3 expression in the course of cardiac hypertrophy rises in moderate hypertrophy but falls in pronounced hypertrophy, so it behaves differently than the expression of SIRT1." (PMID 34899370, 2021). "Elevation of SIRT1 in the heart was previously shown to impart cardioprotection against oxidative stress, inflammation, and cardiac hypertrophy." (PMID 34959644, 2021). "Activation of SIRT1 in cardiomyocytes prevents the development of cardiac hypertrophy, and protects the cells from inflammation and metabolic dysregulation." (PMID 33806509, 2021). "In a failing heart, FGF-21 exerts protective effects, preventing the development of cardiac hypertrophy and ischemic injury via the Sirt1 (sirtuin-1) pathway." (PMID 33520013, 2021). "We demonstrated that GB markedly suppressed cardiac hypertrophy, autophagy, and oxidative stress and activated the SIRT1-FoxO1 pathway in H9c2 cells." (PMID 34257705, 2021). "SIRT1 prevents cardiac hypertrophy, and protects against inflammation and metabolic dysregulation through interaction with PPARα and PGC1α." (PMID 33806509, 2021).